EPHA6 (EPH receptor A6)
Description:
Receptor tyrosine kinase which binds promiscuously GPI-anchored ephrin-A family ligands residing on adjacent cells, leading to contact-dependent bidirectional signaling into neighboring cells. The signaling pathway downstream of the receptor is referred to as forward signaling while the signaling pathway downstream of the ephrin ligand is referred to as reverse signaling (By similarity).
Synonyms: EHK-2; EK12; EHK2; HEK12; FLJ35246; EPA6; PRO57066
Tractability: Small molecule: an approved drug acts on it; a high-quality ligand is known; it belongs to a druggable protein family. Antibody: its Gene Ontology location is reachable by antibodies, with high confidence; UniProt predicts a signal peptide or a membrane-spanning region. PROTAC: a small molecule that binds it is known.
Target class: Tyrosine protein kinase Eph family; Protein Kinase; TK protein kinase group; Kinase; Enzyme
Gene: Protein-coding gene on chromosome 3 (96,814,581 to 97,761,532, forward strand). Ensembl gene ENSG00000080224.
Subcellular location: Membrane
Subcellular location (Human Protein Atlas): Mid piece
Pathways (Reactome):
Developmental Biology: EPH-Ephrin signaling; EPH-ephrin mediated repulsion of cells; EPHA-mediated growth cone collapse
Gene Ontology:
Molecular function: protein binding; transmembrane-ephrin receptor activity; ATP binding; ephrin receptor activity; protein kinase activity; protein tyrosine kinase activity; transmembrane receptor protein tyrosine kinase activity
Biological process: axon guidance; ephrin receptor signaling pathway; cell surface receptor protein tyrosine kinase signaling pathway
Cellular component: dendrite; plasma membrane; membrane
Genetic constraint (gnomAD): Loss-of-function variants: 43 observed, 87.63 expected, observed/expected ratio (o/e) 0.49, 90% interval 0.38 to 0.63. The upper end of that interval is the gene's LOEUF score, 0.63, which puts it in group 2 of 6, group 1 being the genes least tolerant of losing a copy. Missense variants: 1,163 observed, 1,330.4 expected, observed/expected ratio (o/e) 0.87, 90% interval 0.83 to 0.92. Synonymous variants: 490 observed, 464.23 expected, observed/expected ratio (o/e) 1.06, 90% interval 0.98 to 1.14.
Homologues: Orthologues: chimpanzee EPHA6 (99% identical), macaque EPHA6 (99% identical), pig EPHA6 (97% identical), rabbit EPHA6 (96% identical), mouse Epha6 (95% identical), rat Epha6 (95% identical), tropical clawed frog epha6 (75% identical), zebrafish epha6 (67% identical), dog EPHA6 (37% identical). Paralogues in human: EPHA3 (55% identical), EPHA5 (54% identical), EPHA4 (53% identical), EPHA7 (52% identical), EPHA8 (49% identical), EPHB1 (48% identical), EPHB3 (48% identical), EPHB2 (47% identical), EPHA2 (43% identical), EPHB4 (42% identical), EPHA10 (39% identical), EPHA1 (37% identical), and 41 more.
Diseases named in the same sentence as EPHA6 in open-access papers:
EPHA6 is named in the same sentence as 47 diseases in open-access papers, as found by Europe PMC text mining. Sharing a sentence is not in itself a finding about the gene and the disease. The quoted sentences say what the papers report.
prostate carcinoma (9 papers, 2015 to 2024). A carcinoma that arises from epithelial cells of the prostate gland. "NONO is highly expressed in prostate cancer and promotes the development of castration-resistant prostate cancer by causing differential splicing of EPHA6." (PMID 37370134, 2023). "Information regarding the expression and role of EPHA6 in tumors is limited to a few studies, such as breast carcinoma, thymic epithelial tumors, and prostate cancer, where it might be implicated in angiogenesis and vascular invasion." (PMID 35626181, 2022). "Increased EphA6 expression has been described as a poor independent prognostic factor in breast cancer and has been associated with disease progression in prostate cancer patients, where it might be implicated in angiogenesis and vascular invasion." (PMID 34943502, 2021). "The knockdown of EPHA6 decreased prostate cancer cell invasion in vitro and reduced lung and lymph node metastasis in vivo." (PMID 33833937, 2021). "The EphA receptors that are decreased or lost in prostate cancer include EphA5 in patients with a Gleason score of 8, EphA6 in LNCaP-19 cell line, and EphA7 in prostate tumor specimens." (PMID 29682554, 2018). "While EphA1 abundance was decreased in prostate cancer cell lines, EphA2, EphA5, EphA6, EphA7, EphA8, and EphA10 levels were elevated in some of the prostate cancer cell lines as compared to the normal prostate cell line." (PMID 29682554, 2018). "We then divided the 112 prostate cancer cases into 2 groups based on the EphA6 mRNA expression levels in tumor tissues." (PMID 26041887, 2015). "Finally, EphA6 has been identified as a metastasis gene and positively correlated with the progression of prostate cancer, by facilitating invasiveness and angiogenesis." (PMID 33430066, 2021). "Moreover, NONO promotes prostate cancer growth by inducing aberrant RNA splicing of EPHA6, resulting in the truncated EPHA6-001 variant." (PMID 38303029, 2024). "EphA6 knockdown decreased Akt and thereby the PI3K/Akt pathway, which contributes to prostate cancer progression, as well as EIF5A2, a target gene for Akt, which promotes melanoma cell invasion; this indicates that EphA6 may mediate its effects via interaction with the PI3K/Akt pathway." (PMID 33430066, 2021).
breast carcinoma (5 papers, 2021 to 2024). "High EPHA6 expression was associated with a lower OS rate in patients with breast cancer and our RC (HR = 1.11)." (PMID 33833937, 2021). "The 12 protein-coding genes upregulated in positive margin group included several well-known tumor markers for breast cancer (EEF1A2, EPHA6, FOXN4, SOX15)." (PMID 38038766, 2024). "For example, EPHA6 (CHEMBL4526), plays an important role in the formation of breast cancer and poses a new therapeutic target for patients with ER-negative and HER2 positive." (PMID 35379165, 2022).
colon cancer (3 papers, 2006 to 2024). "For example, a dramatic 94-fold decrease in EPHA6 expression has been observed in colorectal tumors when compared to normal tissue, and EPHA8 expression has been detected only in colon tumor but not in corresponding normal tissue." (PMID 16740153, 2006).
glioma (3 papers, 2009 to 2022). A benign or malignant brain and spinal cord tumor that arises from glial cells (astrocytes, oligodendrocytes, ependymal cells). "We have also reported that the tyrosine kinase Eph receptor A6 (EPHA6) promotes apoptosis in BMP-2-sensitive glioma-initiating cells." (PMID 35693928, 2022).
Alzheimer disease (2 papers, 2018 to 2024). A progressive, neurodegenerative disease characterized by loss of function and death of nerve cells in several areas of the brain leading to loss of cognitive function such as memory and language. "In addition, altered alternatively splicing of the EPHB6 gene (located on chromosome 7q34 in the vicinity of the EPHA1 gene) has been associated with Alzheimer’s disease risk and a rare autosomal EPHA6 copy number gain was found to co-segregate with familial Alzheimer’s disease status." (PMID 39706267, 2024).
cervical cancer (2 papers, 2022). A primary or metastatic malignant neoplasm involving the cervix. "To further validate the observation, we performed RT-PCR to detect the transcripts encoding EPHB1 and its isoform EPHA6, well known transcripts regulating axonogenesis and neuronal growth in exosomes of cervical cancer cells." (PMID 35148692, 2022). "For example, the gene Erythropoietin-producing human hepatocellular (EPH) receptors, such as EPHA6 has pro-tumorigenic effects and induces a number of cellular processes, such as adhesion, proliferation, differentiation during carcinogenesis of cervical cancer." (PMID 34991439, 2022).
Intellectual disability (2 papers, 2018). "Similar to NONO, EPHA6 ablation or mutation is associated with behavioral deficits in mice and intellectual disability in humans." (PMID 29535823, 2018).
melanoma (2 papers, 2015 to 2021). A malignant, usually aggressive tumor composed of atypical, neoplastic melanocytes. "EIF5A2, an AKT target gene which promotes melanoma cell invasion, has decreased expression following EphA6 knock-down." (PMID 26041887, 2015).
neuropathy (2 papers, 2015 to 2021). A disorder affecting the nervous system that manifests with pain, tingling, numbness, and/or muscle weakness. "On the other hand, CYP2C8, ABCB1, EPHA5, EPHA6 and TUBB2A were found to be associated with taxane-induced neuropathy in more than one study, but not to be associated with platinum-induced neuropathy." (PMID 26269716, 2015).
Anophthalmia (1 paper, 2020). Absence of the globe or eyeball. "The phenotype of our patient suggests that the retinal degeneration and anophthalmia may be related to the defect of EPHA6 through disruption of RGC organization and retinal axon guidance." (PMID 32344861, 2020). "In proband 1, a boy with DD and anophthalmia, the BCT disrupted EPHA6 gene." (PMID 32344861, 2020).
Anxiety (1 paper, 2023). Intense feelings of nervousness, tension, or panic often arise in response to interpersonal stresses. "Taken together, the alteration in the Epha6 gene expression can affect cognition and memory, thus contributing to anxiety-like behavior." (PMID 37542675, 2023).
atherosclerosis (1 paper, 2022). A disease characterized by the build-up of fatty material and calcium deposition in the arterial wall resulting in partial or complete occlusion of the arterial lumen. "EPHA6 gene is predicted to enable transmembrane-ephrin receptor activity and is found to be associated with insulin signaling and blood pressure phenotype, which are the known risk factors of atherosclerosis." (PMID 36539828, 2022).
benign prostate hyperplasia (1 paper, 2015). "EphA6 mRNA expression is higher in 112 CaP tumor samples compared with benign tissues from 58 benign prostate hyperplasia patients." (PMID 26041887, 2015).
brain injuries (1 paper, 2020). "Blocking EphA6 signaling with EphA6-Fc limits cell death after brain injuries." (PMID 32629797, 2020).
colorectal cancer (1 paper, 2021). A primary or metastatic malignant neoplasm that affects the colon or rectum. "EPHA6 (M0: 4.9%, M1: 17.9%; p = 0.028) is an ephrin receptor and has a high frequency of mutations in the group of patients with metastasis, and its association with metastasis has been previously reported for colorectal cancer." (PMID 35003350, 2021).
developmental delay (1 paper, 2020). "In particular, our results suggest novel candidate genes for retinal degeneration with anophthalmia (EPHA6), developmental delay with speech impairment (KLF13), and developmental delay with brain dysembryoplastic neuroepithelial tumor (UBR3)." (PMID 32344861, 2020). "The most interesting genes that were damaged by the BCTs are: EPHA6 (the first case with an optic phenotype in humans), UBR3 (the second case with developmental delay in humans), KLF13 (second case with developmental delay in humans)." (PMID 32344861, 2020).
dyslipidemia (1 paper, 2025). "EPHA6 contributes to HTN via vascular remodeling and dyslipidemia." (PMID 41573461, 2025).
emotional dysregulation (1 paper, 2023). "We identified several molecular markers, including Dgkh, Arfgef3, Kcnh7, Grin2a, Tenm1 and Epha6, implicated in neurodevelopmental deficits and psychiatric conditions featuring impaired cognition and emotional dysregulation." (PMID 37542675, 2023).
Hypertension (1 paper, 2017). The presence of chronic increased pressure in the systemic arterial system. "Despite these limitation, our results show an intriguing association between the EPHA6 rs4857055 TT genotype and increased risk of hypertension." (PMID 29208002, 2017). "In the hypertension group, a significant association was observed between systolic BP and the EPHA6 rs4857055 C > T polymorphism (P = 0.022)." (PMID 29208002, 2017). "The presence of the TT genotype of the EPHA6 rs4857055 C > T SNP was associated with a higher risk of hypertension after adjusting for age, sex, body mass index (BMI), smoking, and drinking [odds ratio 1.533, P = 0.001]." (PMID 29208002, 2017). "The presence of the TT genotype of the EPHA6 rs4857055 C > T SNP was associated with a higher risk of hypertension [OR 1.415 (95% CI 1.129–1.733), P = 0.003]." (PMID 29208002, 2017). "The relative EPHA6 rs4857055 C > T genotype (P = 0.010) and allele frequencies (P = 0.010) in hypertension patients differed significantly from those in the controls." (PMID 29208002, 2017). "The major finding of this study is that the frequency of the EPHA6 rs4857055 TT genotype was significantly higher in hypertensive patients than in controls, suggesting an association between the EPHA6 rs4857055 C > T SNP and hypertension." (PMID 29208002, 2017). "In the hypertension group, trends toward associations were observed between serum triglyceride and the EPHA6 rs4857055 C > T polymorphism (P = 0.069), between serum apo B and the rs4857055 C > T polymorphism (P = 0.015), and between LDL particle size and the rs4857055 C > T polymorphism (P < 0.001)." (PMID 29208002, 2017). "From the twenty-five most strongly associated SNPs for hypertension, EPHA6 rs4850755 was the most highly associated SNP with both systolic BP (P = 2.63E-08) and diastolic BP (P = 3.67E-05); therefore, we performed an association analysis on rs4857055 in EPHA6." (PMID 29208002, 2017). "In the hypertension group of this study, subjects with the EPHA6 rs4857055 TT genotype showed a higher tendency of serum triglyceride and significant increases in apo B than those with the CC or CT genotype." (PMID 29208002, 2017). "Based on several studies that have shown that Ephs, particularly Eph A members, are key modulators of BP, we could presume that EphA6 is another important protein for hypertension development." (PMID 29208002, 2017). "The results of this study suggest that the EPHA6 rs4857055 C > T SNP could be a novel candidate gene for hypertension; moreover, the EPHA6 rs4857055 TT genotype could be associated with hypertriglyceridemia and small LDL particle size in hypertension." (PMID 29208002, 2017). "The objective of the present study was to determine whether EPHA6 is a novel candidate gene for hypertension in a Korean population." (PMID 29208002, 2017). "Therefore, the objective of the present study was to determine whether EPHA6 is a novel candidate gene for hypertension in the Korean population." (PMID 29208002, 2017).
hypertriglyceridemia (1 paper, 2017). A laboratory test result indicating elevated triglyceride concentration in the blood. "In the present study, the EPHA6 rs4857055 TT genotype showed markedly higher triglyceride levels, a phenomenon (hypertriglyceridemia) that could result in strong VSMC contraction, leading to increased BP." (PMID 29208002, 2017).
infarction (1 paper, 2014). A localised pathological necrosis of tissue resulting from obstruction of the blood supply usually by a thrombus, an embolus, or vascular torsion. "Similar to uninjured STZ hearts, ephrinA1 and EphA6 were higher among EphA2-R-M STZ hearts after infarction." (PMID 25166508, 2014).
memory impairment (1 paper, 2020). "Mild DD present in our patient is also compatible with the phenotype of EphA6-/- mice (learning and memory impairment)." (PMID 32344861, 2020).
myocardial infarction (1 paper, 2015). Gross necrosis of the myocardium, as a result of interruption of the blood supply to the area, as in coronary thrombosis. "In addition, EphA6 mRNA is down-regulated in the myocardium of adult mouse after myocardial infarction." (PMID 26041887, 2015).
Obesity (1 paper, 2017). Accumulation of substantial excess body fat. "Furthermore, previous studies have identified associations of EPHA6 with obesity-related traits, and the control of glucose homeostasis has emerged as a role of the EphA/ephrin-A system." (PMID 29208002, 2017).
pulmonary fibrosis (1 paper, 2025). Chronic progressive interstitial lung disorder characterized by the replacement of the lung tissue by connective tissue, leading to progressive dyspnea, respiratory failure, or right heart failure. "The second lung fibrosis-correlated EV protein, Q9UF33 (encoded by the EPHA6 gene), is implicated in the severity of bleomycin-induced pulmonary fibrosis in mice." (PMID 41279897, 2025).
retinal detachment (1 paper, 2022). An eye emergency condition which may lead to blindness if left untreated. "On the other hand, EPHA6 immunohistochemical expression in UMs was associated with older age and the absence of retinal detachment." (PMID 35626181, 2022). "High nuclear EPHA6 IRS was correlated with older age at diagnosis (Mann–Whitney U test, p = 0.03) and the absence of retinal detachment (Fischer’s exact test, p = 0.05)." (PMID 35626181, 2022).
substance dependence (1 paper, 2021). The psychological or physiological need to take a substance in order to experience its effects or to avoid the effects of its absence. "Genes located in substance dependence, signal transduction and nervous functions pathways were down‐regulated: Cacna2d3, Epha6, Nedd4l and Vav2." (PMID 34196487, 2021). "Genes located in substance dependence, Signal transduction and also nervous functions pathways were down‐regulated: Cacna2d3, Epha6, Nedd4l and Vav2." (PMID 34196487, 2021).
thymic neoplasia (1 paper, 2021). "EphA6 is not expressed in normal thymus according to gene expression data, but it is uniformly positive in both epithelial and lymphoid cells of all thymoma subtypes by immunohistochemistry; therefore, EphA6 could be considered a potential oncogenic driver in thymic neoplasia." (PMID 34943502, 2021).
thymoma (1 paper, 2021). A neoplasm arising from the epithelial cells of the thymus. "EphA4 and EphA6 displayed higher epithelial expression in thymoma subtypes B2 and B3 as well as thymic cancer compared with subtypes A and AB (p = 0.011 and p < 0.001 for EphA4 and EphA6, respectively)." (PMID 34943502, 2021).